MITF (melanocyte inducing transcription factor)
Diseases named in the same sentence as MITF in open-access papers (continued):
Sharing a sentence is not in itself a finding about the gene and the disease.
melanoma (continued). "Evaluation of Tumor Cancer Genome Atlas (TCGA) database confirms our experimental data as reduced MITF and OPN4 expression in human melanoma correlates with slower cell cycle progression and presence of immune cells in the tumor microenvironment (TME)." (PMID 35562405, 2022). "In melanoma, sirtuin expression is indirectly downregulated by PI3K, via MITF repression, and their inhibition favors a proliferation arrest and an activation of programmed cell death, while it also compromises the cells’ invasive potential." (PMID 35409020, 2022). "Because of their demonstrated interactions with MITF, it will be important to conduct more extensive functional studies of both SMARCD1 and SMARCD2 during melanocyte development and in melanoma." (PMID 35323214, 2022). "Primary tumors developed from the MITF-methylated SOX10+ and SOX10– melanoma cells were molecularly different and had different preferential metastatic spread." (PMID 36040798, 2022). "Moreover, validating previous reports, the subset of cell lines with decreased MITF gene expression was enriched with cases harboring MITF promoter methylation, suggesting that epigenetic mechanisms are crucial in the regulation of the melanoma cell differentiation state." (PMID 36040798, 2022). "On the other hand, miR-211 can block the invasion and migration of melanoma cells, and repress POU3F2 (POU-domain class 3 transcription factor 2, also known as brain-specific homeobox 2 (BRN2)) which acts as a MITF suppressor." (PMID 36224606, 2022). "The melanocyte differentiation gene MITF and the proapoptotic factor SOX9 were negatively regulated by GDF6, which blocked melanoma differentiation, inhibited cell death, and promoted tumor growth." (PMID 36253873, 2022). "The heterogeneity of MITF levels in melanoma restricts the essential role of DUSP4 to high- and moderate-MITF–expressing cells." (PMID 35580987, 2022). "The diverse roles of MITF, its upstream regulators, and MSX1 highlight that factors expressed during NC cell and melanocytic development contribute to melanoma cell plasticity." (PMID 34071193, 2021). "Taken together, morin promoted melanin production by upregulating MITF and its downstream pathways, TRP-1 and TRP-2, in B16F10 mouse melanoma cells." (PMID 33917985, 2021). "During treatment, when melanoma cells bypass BRAF inhibition, MITF expression inversely correlates with AXL, a TKRs family member." (PMID 33922284, 2021). "On average, MITF expression is reduced whereas the AXL expression level increased in the metastatic melanoma group, validating that MITFlow/AXLhigh melanoma cells represent metastatic melanoma more closely." (PMID 37849907, 2021). "MITF expression is modulated through β-catenin and another key effector in the Wnt pathway called lymphoid enhancer-binding factor 1 (LEF1) in melanoma cells." (PMID 33647315, 2021). "MITF can regulate cell cycle progression by modulating cyclin-dependent kinase-2 (CDK2), which is important for melanoma clonogenic growth." (PMID 33746605, 2021). "MITF and EGFR are expressed in melanoma cells in a mutually exclusive manner, and MITF was described previously to suppress TGFA expression." (PMID 33916908, 2021). "The high ZEB1/TWIST1, low MITF, high AXL state promotes an invasive, dedifferentiated phenotype in melanoma while the high ZEB2/SLUG, high MITF, low AXL state promotes an anti-invasive, proliferative, differentiated phenotype." (PMID 35008286, 2021). "A large number of other melanocytic markers have been subsequently investigated including HMB45, Melan A, tyrosinase, MITF, and SOX10, and are increasingly used in the diagnosis of melanoma." (PMID 34449584, 2021). "Despite this central role, significant variation in mitochondrial content and function exists in melanoma, often regulated by MITF (melanocyte inducing transcription factor) and PGC-1 (the peroxisome proliferator-activated receptor gamma coactivator 1 alpha)." (PMID 34567159, 2021).
melanoma (continued). "The induction of MLANA was confirmed to be dependent on MITF, since depletion of MITF using siRNA prevented the irradiation-dependent increase in MLANA expression in human melanoma cell lines." (PMID 33789714, 2021). "This compound significantly reduced the mRNA and protein expression levels of MITF, TRP-1, and tyrosinase in α-MSH-stimulated B16F10 murine melanoma cells." (PMID 34946631, 2021). "Based on this initial observation of HuR-NP reducing MITF, we conducted combinatorial studies using U0126, a MEK1/2 inhibitor, to emulate clinical studies conducted for treating melanoma patients." (PMID 33418925, 2021). "This compound potently suppressed melanin synthesis by ten times more than arbutin via the regulation of MITF, tyrosinase expression and CREB signaling pathways in murine melanoma B16-F10 cells." (PMID 34946631, 2021). "What is the frequency of melanoma and/or mesothelioma co-occurring with renal neoplasia and of germline alterations of BAP1 and MITF within this cohort?" (PMID 34767027, 2021). "The results revealed that irradiation increased expression of both proteins, a result also reflected in the radiation-induced increased expression of MITF and MLANA in human SK-MEL-28 melanoma cells." (PMID 33789714, 2021). "In this study, we have shown that MITF directly binds to and represses the expression of ECM, EMT and focal adhesion genes in human melanoma cells." (PMID 33438577, 2021). "Meanwhile, we also turned to TCGA Skin Cutaneous Melanoma (SKCM) database to analyze the correlation between CD27-AS1 level and the expressions of MITF, TYR and PMEL in melanoma." (PMID 35096622, 2021). "To gain further insight in the regulation of ADAM10 by MITF, we established human IGR37 melanoma cells in which MITF was knocked out using CRISPR/Cas9." (PMID 33789714, 2021). "MITF is a downstream target of EP300, a histone acetyltransferase and an oncogene in a subset of melanomas." (PMID 33556121, 2021). "In melanoma, specifically, NFIB-targeted upregulation of EZH2 led to the epigenetic silencing of MITF, promoting a highly invasive phenotype." (PMID 34922631, 2021). "We examined TNFα effects on melanoma differentiation by analyzing the accumulation of the key marker proteins MITF, Melan A, AXL and NGFR in the 40 melanoma cell lines." (PMID 34073253, 2021). "KIT encodes the receptor tyrosine kinase c-KIT that is involved in various signaling pathways in melanoma including melanocyte development, MAPK/ERK signaling, PI3K/AKT signaling, and MITF upregulation." (PMID 35008286, 2021). "Taken together, our results suggest that morin enhances melanin production by upregulating MITF through the activation of ERK and p38 signaling pathways in B16F10 mouse melanoma cells." (PMID 33917985, 2021). "This suggests that MITF enables epithelial to mesenchymal plasticity (EMP) that allows the formation of a hybrid state between EMT and MET to enforce the aggressiveness of melanoma." (PMID 33438577, 2021). "In an effort to determine the clinical relevance of the findings above in vivo, the relationship between GLI1/2, MITF, and EGFR was determined in the TCGA melanoma cohort." (PMID 34572373, 2021). "In this work, we show that BRN2 acts as a tumor suppressor during melanoma initiation and progression in a BRAF-PTEN context since BRN2 and MITF regulate positively and negatively the transcription of PTEN, respectively." (PMID 34140478, 2021). "Treatment with BRAFi leads to MITF dependent regulation of PGC1α, which subsequently promotes mitochondrial biogenesis, OXPHOS and response to oxidative stress in BRAFV600 melanoma cells." (PMID 34830962, 2021). "In summary, NRF2 initiates a mechanism that leads to the maintenance of melanoma cells with high EGFR and low MITF levels, where NRF2 and EGFR pathways enhance each other in a positive feedback loop." (PMID 33916908, 2021).
melanoma (continued). "In myeloid precursor cells, MITF was shown to interact with EOS to recruit co-repressors to target genes, whereas in melanoma cells MITF bound directly to an E-box located in an enhancer of the c-JUN gene, leading to reduced expression of the gene." (PMID 33438577, 2021). "Since DIRC3 expression is negatively correlated with both MITF and SOX10 levels, its expression increases in invasive MITFlow melanoma cells." (PMID 34638331, 2021). "Thus, whether MITF promotes or suppresses melanoma remains ambiguous." (PMID 34071193, 2021). "In this study, we show that MITF represses the expression of focal adhesion and ECM genes in melanoma cells and tissues." (PMID 33438577, 2021). "Another AP-1 family member, Fra1 (FOSL1), downregulates MITF through its transcriptional target, the chromatin modifier HMGA1, and induces the expression of AXL, driving melanoma cells to the MITFlow/AXLhigh state." (PMID 34604096, 2021). "Bcl-2, a pro-apoptotic protein, regulates the expression of MIR211 by modulating MITF expression in melanoma cell lines, in addition to the reciprocal regulation of BCL2 by MITF." (PMID 33628737, 2020). "Differentiated osteoblasts in turn can support melanoma cell proliferation and survival via the secretion of RANKL that elevates the levels of the transcription factor MITF, even in the presence of BRAF inhibitor." (PMID 31323160, 2020). "S-100 is a highly sensitive marker for melanoma; HBM-45, melan-A, MITF and tyrosinase are highly specific markers for this entity." (PMID 32724562, 2020). "As target genes of MITF, 3 subunits of V-ATPase including ATP6V1G1, ATP6V1C1, and ATP6V0D2, are highly expressed in melanoma cells." (PMID 32867178, 2020). "In view of the correlation between β-catenin and MITF expression, WNT-signaling also affects melanoma plasticity." (PMID 32659938, 2020). "In this study, we show that the MITF, TFEB and TFE3 transcription factors are all produced in melanoma cells, albeit at different levels." (PMID 32881934, 2020). "Our study also demonstrated that the effects of BEA and BEA G1 are associated with the suppression of molecular targets, which play crucial roles in melanoma oncogenesis, including ERK, JNK, p38, NF-κB, STAT3, and MITF." (PMID 32340351, 2020). "Our results suggest that, in particular, MITF- and PTEN-negative melanoma tumors have molecular properties rendering them resistant to targeted- and immuno-therapy." (PMID 32245160, 2020). "Subsequent immunoblot assay showed that the expression of MITF was increased in melanoma cells with POU4F1 overexpression and decreased in melanoma cells with POU4F1 knockdown, proving that the expression of MITF was regulated by POU4F1." (PMID 32532957, 2020). "Pathologists look for a melanoma cocktail antibody [most commonly S-100, human melanoma black (HMB)-45, Melan-A, and microphthalmia transcription factor (MITF)]." (PMID 33585548, 2020). "In conclusion, our study demonstrates that POU4F1 is up-regulated in the melanoma cells, which promotes the resistance to BRAFi by the activation of MEK/ERK pathway and MITF." (PMID 32532957, 2020). "We further reported that GH upregulates the expression and activity of melanocyte-inducing transcription factor (MITF) via JAK2-STAT5 and SRC signaling in human melanoma cells, thereby inducing drug sequestration in melanosomes." (PMID 33291663, 2020). "In conclusion, two independent strategies of motif analysis suggest conservation of TF binding sites for known melanoma master regulators, with conserved SOX10, MITF, TFAP2A, and ETS TF family motif enrichment in MEL enhancers across all six studied species." (PMID 32732264, 2020). "MITF had a positive correlation with its target ANXA1 in lung adenocarcinoma, but had an inverse correlation in melanoma." (PMID 33293474, 2020). "Our study provides the evidence for the contribution of POU4F1 to the resistance of melanoma cells to BRAFi via activating MEK/ERK pathway and MITF." (PMID 32532957, 2020).
melanoma (continued). "Negative staining for cytokeratins and melanoma markers such as Melan-A, MITF, or HMB45 can be helpful in distinguishing MPNST from carcinomas and melanoma, respectively." (PMID 32642731, 2020). "We extended our studies to human melanoma cells where treatment with JQ1 potentiated expression of gp100 and MITF." (PMID 32231230, 2020). "Surprisingly, additional mechanisms promoting glycolysis in melanoma involve both the activation and the inhibition of the transcriptional factor and OXPHOS inducer MITF." (PMID 32528879, 2020). "Finally, upon RNA sequencing of G007-LK-treated human melanoma cell lines and B16-F10 cells, we reveal a transcriptional response profile for a cell line subpopulation displaying high relative baseline YAP signaling activity and predisposition for reduced MITF expression upon tankyrase inhibition." (PMID 32332858, 2020). "Induction of MITF and depletion of COX2 and PGE2 were also observed in NRF2-deleted melanoma cells in vivo." (PMID 32978520, 2020). "In contrast to melanoma patients, lung adenocarcinoma (LUAD) patients with high MITF expression had longer survival time than those with low MITF expression (p < 0.05, log-rank test)." (PMID 33293474, 2020). "In this study, a combination of Al and Gg extracts was investigated for cellular tyrosinase inhibitory activity, reduction of melanin contents and downregulated expression of melanogenesis-related genes MITF, TYR, TRP-1 and TRP-2 in melanoma B16 cells." (PMID 33066628, 2020). "Like MITF, the TFEB and TFE3 genes are expressed in melanoma cells as well as in melanoma tumors, albeit at lower levels." (PMID 32881934, 2020). "It is known that high levels of MITF, APOE, and SPP1 mark different aspects of melanoma progression, i.e., melanocyte differentiation, angiogenesis, and inflammation, respectively." (PMID 33202765, 2020). "Evidence for cobinding of SOX10, MITF, and TFAP2A was previously observed by enrichment of both MITF and TFAP2A motifs in SOX10 ChIP-seq data in melanoma cells." (PMID 32732264, 2020). "In response to ERK and MEK inhibition, AXL/MITF-mediated drug resistance is observed among mutant BRAF and NRAS melanoma cell lines." (PMID 32245042, 2020). "In human melanoma cells (HMV-II), the expression of tyrosinase and MITF was reduced after treatment with citric acid, aligning with the intracellular melanin content of HMV-II cells." (PMID 33332393, 2020). "In melanoma patients, the SAMMSON locus is recurrently co-gained with the MITF oncogene through 3p13-3p14 focal amplification." (PMID 33329688, 2020). "Taken together, these results demonstrate that LEO and REO treatment leads to ubiquitination and proteasomal degradation of MITF through ERK1/2 activation, which eventually suppress melanin production in melanoma cells." (PMID 33260669, 2020). "However, due to the retrospective nature of this study, standardized information on pigmentation was not available, and therefore we could not assess the impact of RHC variants on melanoma pigmentation according to MITF germline status." (PMID 32054529, 2020). "In a screen for lncRNAs targeted by the melanoma transcription factors MITF and SOX10, DIRC3 was identified as a top hit and characterized as a melanoma tumor suppressor." (PMID 33329688, 2020). "Concerning the histotype of first melanoma, MITF+ patients showed a higher rate of nodular melanomas than MITF− patients (32% and 19%, respectively, p = 0.04)." (PMID 32054529, 2020). "Collectively, these data indicate that MITF and TFEB are able to regulate each other’s mRNA and protein expression in human 501Mel and Skmel28 melanoma cells." (PMID 32881934, 2020).
melanoma (continued). "PLX4032 has been also reported to modify MITF activity and expression in certain melanomas, including the highly invasive BRAFV600E mutant COLO829 melanoma line, resulting in a MITF-High/AXL-Low phenotype." (PMID 33202765, 2020). "Nelfinavir has been identified as a potent suppressor of PAX3 and MITF expression and sensitizer of BRAF and NRAS mutant melanoma cells to MAPK pathway inhibitors." (PMID 33322354, 2020). "MITF is considered a crucial factor in melanoma invasiveness and plays a critical role in controlling BRAFV600E melanoma." (PMID 33202765, 2020). "Relating these miRNAs with the main molecular deregulated pathways, e.g. the RAS/MAPK pathway, the MITF pathway, the p16INK4A-CDK4-RB pathway, and the PI3K-AKT pathway, would offer new insights in deciphering the aggressive and metastatic feature of melanoma." (PMID 32185171, 2020). "In melanoma cells, stable SOX10 knockout contributes to G1 phase arrest and the reduced expression of MITF and p21 but elevates p27." (PMID 33344444, 2020). "The authors observed the downregulation of both MITF and SCD in melanoma cells following glutamine deprivation with an alteration of the balance of saturated fatty acids and MUFAs." (PMID 33202944, 2020). "We treated SB-3123p melanoma cells with either JQ1, BI-2536, Fenobam or PHA-793887 and found that the 4 compounds up-regulated the transcription of MITF and its target genes, DCT, Tyrp, Melan A and Pmel-1 in a dose dependent fashion as determined by qPCR." (PMID 32231230, 2020). "In in vivo melanoma models, MAPK-targeted agents induce tumor necrosis factor α (TNFα) production by macrophages, which promotes NFkB pathway activation and higher MITF expression." (PMID 33036192, 2020). "The SCD1 inhibitor A939572 was also shown to prevent the proliferation of the MITF-high/proliferative IGR37 and 501mel melanoma cell lines." (PMID 33121001, 2020). "Over the entire cohort, melanoma-specific survival (MSS) was influenced by CD2, PDL1 (CD274), and MITF (p = 0.01, p = 0.003, p = 0.03, respectively)." (PMID 33003444, 2020). "Overall, by regulating MITF-dependent phenotype switching, dysregulation of the EMT-TF network contributes to malignant progression of melanoma." (PMID 32759677, 2020). "In this study, our data showed that 5-HT regulated the expression of MITF and TYR in B16F10 melanoma cells by specifically activating PKA/p-CREB signaling pathways." (PMID 32961761, 2020). "Further, a downstream target of PI3K, melanocyte inducing transcription factor (MITF), has been found to regulate SIRT1 levels in melanoma cells." (PMID 33178616, 2020). "To decipher the effects of ACF on MITF expression, we next analyzed the phosphorylated forms of ERK1/2 and CREB in melanoma cells." (PMID 33396270, 2020). "The distribution of PTCH1 gene expression level for all TCGA patients compared to genes known to be well expressed in melanoma (GAPDH, ACTB, MITF) indicates that PTCH1 is well expressed in primary and metastatic samples." (PMID 32526884, 2020). "Taken together, these data indicate osteoblast‐derived RANKL alters the balance of death and proliferation that occurs when melanoma cells are treated with BRAF inhibitor to decrease apoptosis and increase cell‐cycle entry via upregulation of MITF." (PMID 31323160, 2020). "Here we show that MITF binds the CLEAR-box element in the promoters of lysosomal and autophagosomal genes in melanocytes and melanoma cells." (PMID 30705290, 2019). "Since MITF/TFE family factors can regulate lysosomal signaling, including Wnt/β-catenin we studied TFEB and βcatenin levels in V600BRAF melanoma cell lines." (PMID 30634982, 2019). "In order to determine if our observations result in an upregulated MITF activity, we chose to assay the tyrosinase activity as well as the melanin production rate in GH treated or GHR-blocked melanoma cells, in presence of multiple classes of anticancer drugs." (PMID 31547367, 2019).